CD34 (CD34 molecule)
Diseases named in the same sentence as CD34 in open-access papers (continued):
Sharing a sentence is not in itself a finding about the gene and the disease.
acute myeloid leukemia (continued). "CTLA-4 expression was also evaluated in CD34+ cells from patients with myelodysplastic syndrome, chronic myelomonocytic leukemia, and acute myeloid leukemia." (PMID 31911758, 2020). "The involvement of the JAK/STAT signaling pathway in CD34+ cell proliferation is important in several hematologic neoplasms, including myelodysplastic syndromes and acute myeloid leukemia (AML)." (PMID 32265915, 2020). "We also examined the effects of lncNR4A3 in CD34+ hematopoietic cells from two acute myeloid leukemia patients." (PMID 33330042, 2020). "Although CD34 is considered a marker of normal hematopoietic stem cells and for some acute myeloid leukemia, its expression is not limited to such cells." (PMID 32010428, 2020). "This HIV-1 infected patient, who now has an undetectable viral load, underwent allogeneic CD34+ HSPC transplantation for acute myeloid leukaemia (AML) with HLA-matched cells from a donor homozygous for the Δ32 CCR5 allele." (PMID 32034584, 2020). "LSCs were first identified in Acute Myeloid Leukemia (AML) within the CD34+/CD38− cell population and defined as cells that can engraft and initiate AML in a NOD/SCID immunodeficient host mouse." (PMID 31717629, 2019). "The early immature CD34+ acute myeloid leukemia (AML) cell subpopulation-acute myeloid leukemia progenitor cells (APCs), is often resistant to conventional chemotherapy, making them largely responsible for the relapse of AML." (PMID 30909158, 2019). "On these grounds, and because our results include distinct human acute myeloid leukemia cell lines and primary cultures of normal human CD34+-HPCs, we can conclude that upregulation of miR-125a-5p is crucial for neutrophil differentiation." (PMID 31523391, 2019). "We demonstrate that transplants of bone marrow patient-derived acute myeloid leukemias (hAMLs) grow very similarly in the humanized (hCB)-CD34+ NSG and parental NSG mice." (PMID 31536492, 2019). "Myelodysplastic syndromes (MDS) and acute myeloid leukaemia (AML) are characterised by abnormal differentiation of bone marrow haematopoietic stem cells (HSCs) into immature CD34+ blast cells and ineffective haematopoiesis." (PMID 31870430, 2019). "In the present study the role of VMP1 was analysed in CD34+ cells of cord blood (CB) and primary acute myeloid leukemia (AML) cells and cell lines." (PMID 31142733, 2019). "CSCs were first demonstrated in acute myeloid leukemia (AML) as the tumor cells bearing the surface profile of CD34+CD38− in 1994." (PMID 31336602, 2019). "CSCs were initially identified in acute myeloid leukemia (AML) as a CD34+ CD38- subpopulation capable of initiating leukemia after engraftment in immunodeficient mice." (PMID 29491834, 2018). "Bonnet and Dick first isolated CD34+CD38- cells that are capable of initiating human acute myeloid leukemia (AML)." (PMID 29179522, 2017). "Acute myeloid leukemia initiating cells or stem cells are believed to be restricted in the CD34+ compartment." (PMID 28985760, 2017). "Bonnet and Dick (1997) reported that a small subset of leukemic cells (CD34+CD38-) were capable of initiating human acute myeloid leukemia (AML) in a xenograft mouse model, this provided the first experimental evidence for the existence of cancer stem cells." (PMID 28400729, 2017). "In acute myeloid leukemia, CSCs were shown to express CD34 (Cluster of Differentiation 34) and lack expression of CD38." (PMID 27418931, 2016). "These authors described CD34+/CD38− cancer cells able to initiate acute myeloid leukemia in immunocompromised mice." (PMID 27418931, 2016). "The CD34+ MUTZ-3 acute myeloid leukemia cell line has been used as a dendritic cell (DC) differentiation model." (PMID 26252775, 2015). "We recently found that CD82 inhibits matrix metalloproteinase 9 and augments adhesion of CD34+/CD38− acute myelogenous leukemia (AML) cells to the bone marrow (BM) microenvironment." (PMID 26139471, 2015).
acute myeloid leukemia (continued). "Patients who develop therapy-related myelodysplasia/acute myeloid leukemia after autologous-hematopoietic stem cell (aHCT) transplant show lower expression levels of DNA repair genes in their pre-aHCT CD34+ cells." (PMID 24667872, 2014). "Genes higher in the podoplaninhigh population are expressed in bone marrow, in acute myelogenous leukemia and in stem progenitor cells CD34+ and CD38+." (PMID 25502694, 2014). "For instance, two molecularly distinct populations of leukemic stem cells (LSCs) co-exist and are hierarchically ordered in primary human CD34(+) acute myeloid leukemia; one LSC population gives rise to the other." (PMID 24823879, 2014). "Gene transfer of INPP5D has been shown to reduce proliferation in CD34+ cells from patients with acute myeloid leukemia (AML)." (PMID 23565812, 2013). "The CD34+CD38− surface antigen phenotype is not only specific to tumour stem cells in acute myeloid leukaemia but also to human hematopoietic stem cells." (PMID 23604326, 2013). "Almost two decades later, a CD34+CD38− subpopulation of cells were isolated in acute myeloid leukaemia which, when transplanted into NOD/SCID mice, were capable of initiating acute myeloid leukaemia." (PMID 23533441, 2013). "CSCs were first demonstrated in human acute myeloid leukemia (AML) when investigators found that the ability to initiate tumors by transplantation of AML cells into NOD/SCID mice was limited to a CD34+/CD38− subpopulation of leukemic cells." (PMID 24179490, 2013). "CK2α was found highly expressed in the majority of samples across the different acute myeloid leukemia prognostic subgroups as compared to normal CD34+ hematopoietic and bone marrow cells." (PMID 24283803, 2013). "Drug-induced apoptosis was measured flow cytometrically in primary cells from patients with acute myeloid leukaemia using a CD34/CD71/annexinV gating strategy to identify dormant apoptotic cells." (PMID 23767415, 2013). "In hematopoietic cells, retinoblastoma protein antagonizes the nucleolin-mediated activation of the CD34 promoter in KG1 acute myelogenous leukemia cells." (PMID 22693613, 2012). "The repositioning occurs in established cell lines, in primary human CD34+ hematopoietic progenitors and in primary human acute myeloid leukemia cells." (PMID 21364958, 2011). "Resistance of CSC populations to therapy was first reported in human acute myeloid leukaemia CD34+/CD38− stem cells." (PMID 20332776, 2010). "Existence of CSCs was first documented in acute myelogenous leukaemia, in which only the CD34+/CD38− sub-population of leukaemic cells was shown to proliferate extensively, self-renew, and form new tumours." (PMID 20332776, 2010). "Interestingly, CD34+ HSCs and acute myeloid leukemia cell lines attenuated MSC osteoblastic differentiation upon prolonged direct cell–cell contact." (PMID 39682159, 2024). "Acute myeloid leukemia (AML) is an aggressive heterogenous disease arising from the accumulation and clonal expansion of somatic-driven mutations in CD34+/CD38- hematopoietic progenitors, which demonstrate increased proliferation, survival, and impaired maturation capacity." (PMID 37108308, 2023). "CD34+CD38- CSCs were first recognized in acute myeloid leukemia." (PMID 37509281, 2023). "For example, CD34 is a unique biomarker of acute myeloid leukemia (AML) blasts." (PMID 35215642, 2022). "Initially, Dick and colleagues identified the leukemia-initiating cluster of differentiation (CD)-34+ CD38- cells from acute myeloid leukemia (AML) and showed that these cell fractions have differentiation and self-renewal capacities using serial transplantation in immunodeficient mice." (PMID 35155201, 2021). "Therefore, multiplex analyses of bone marrow biopsies (BMB) from patients with MDS and secondary acute myeloid leukemia (sAML) were performed in order to determine the repertoire of lymphocyte subpopulations and their distance to CD34+ blasts." (PMID 33430322, 2021).
acute myeloid leukemia (continued). "Since the ability to predict disease evolution is crucial for clinical decisions, we studied single-cell genomics and transcriptomics of CD34-positive cells from a primary myelofibrosis (PMF) patient who progressed to acute myeloid leukemia (AML) while receiving Ruxolitinib." (PMID 33542466, 2021). "In addition, ROR1 was found in CD34+ acute myeloid leukemia (AML) cells and can be targeted by mAbs.In addition to hematological malignancies, aberrant expression of ROR1 was also found in a wide range of solid tumors as a biomarker and therapeutic target." (PMID 34123850, 2021). "Additionally, CD34 functions as a stemness marker for acute myelogenous leukemia, which is a hematological malignant tumor with abnormal proliferation of bone marrow hematopoietic cells and is the most common acute leukemia in adults." (PMID 32586050, 2020). "Acute myeloid leukemia (AML) LSCs predominantly reside in the CD34+CD38− fraction." (PMID 32872365, 2020). "Originally identified by mAbs raised against the primitive CD34+ acute myeloid leukaemia cell line KG1a, CD109 is a transforming growth factor (TGF)-β co-receptor that binds TGF-β1, regulates TGF-β receptor endocytosis and degradation, and suppresses TGF-β/Smad signalling." (PMID 29731998, 2018). "In 1994, John Dick and colleagues reported in their historical work that human acute myeloid leukemia is organized in a hierarchical differentiation model, and CD34+CD38− cells are the stem cells of this model and only CD34+CD38− cells can regenerate the disease." (PMID 28415561, 2017). "Showing further experimentally supported the hypothesis through the transfer of tumorigenic properties of CD34+/CD38− human acute myeloid leukemia cells into severe combined immunodeficiency mice (SCID)." (PMID 28785557, 2017). "The phosphoSTAT5 — miR-21 — PDCD4 pathway was active in CML primary CD34+ cells, but also in acute myeloid leukemia (AML) models like MV4.11 and MOLM13, where the constitutively active tyrosine kinase FLT3-ITD plays a similar role to BCR-ABL1 in the K562 cell line." (PMID 29100302, 2017). "CD34+CD38− cells have been shown to be able to initiate acute myeloid leukemia (AML)." (PMID 28018598, 2016). "This was accomplished by Bonnet and Dick in acute myeloid leukemia (AML) who showed that small subset of leukemic cells (CD34+CD38−) was able to initiate the disease when transplanted into a NOD/SCID mouse (non-obese diabetic/ severe combined immunodeficient mouse)." (PMID 26593898, 2015). "They showed that the CD34+/CD38- cells population (phenotype characteristic for hematopoietic stem cells) of acute myeloid leukaemia (AML) is able to form derivative leukaemia after transplantation into NOD/SCID (non-obese diabetic/severe combined immunodeficient) mice." (PMID 25723910, 2014). "CD96 is a promising candidate as a leukemic stem cell (LSC)-specific antigen and is expressed on the majority of CD34+CD38− Acute myeloid leukemia (AML) cells, whereas only a few cells in the normal Hematopoietic stem cell (HSC)-enriched population express CD96 weakly." (PMID 22634835, 2012). "Another gene of interest highlighted by this analysis is CD109 (chromosome 6), a cell surface antigen which was initially studied in CD34 positive acute myeloid leukaemia cell lines, but has subsequently been found to be expressed on a variety of haematopoietic cells and endothelial structures." (PMID 22311740, 2012). "In acute myeloid leukemia the CSC are considered to be within the CD34+/CD38− population." (PMID 24281171, 2010). "DCPs from cancer patients including multiple myeloma, acute myeloid leukemia, acute lymphoblastic leukemia, Hodgkin's lymphoma and glioblastoma patients have been successfully generated from a small number of BM CD34+ HPCs over several orders of magnitude ( > 106) (unpublished)." (PMID 21106069, 2010).
acute myeloid leukemia (continued). "In this study, we investigated the reciprocal direct interaction between MSCs and CD34+ HSCs under physiological conditions and hematological malignancies such as acute myeloid leukemia (AML)." (PMID 39682159, 2024). "The initially isolated KG1 cell line has been widely used in the literature, and its characteristics recapitulate major features of minimally differentiated (CD34+) acute myeloid leukemia (AML) cells." (PMID 36416440, 2023). "The study of CSCs began in 1994, when it was reported that CD34/CD38 cells were human acute myeloid leukemia (AML) stem cells." (PMID 35571530, 2022). "In particular, the HSC and GMP seem to be the more “stressed” cells in the MDS microenvironment; nevertheless, in most cases of acute myeloid leukemia, the primary AML CD34+ cell belongs to these two subpopulations." (PMID 36644527, 2022). "In order to find out its role in acute myeloid leukemia (AML) pathogenesis, we first analyzed the expression levels of 10 key genes involved in ketone metabolism in AML blasts and CD34+ hematopoietic stem cells (HSCs) from healthy donors." (PMID 34150668, 2021). "CSCs were first isolated (CD34+CD38−) from Acute Myeloid Leukemia (AML) patient samples in late 90s." (PMID 32296643, 2020). "CD34 antigen, a unique marker of AML blasts, was used to isolate TEX from the plasma of patients with acute myeloid leukemia." (PMID 32709086, 2020). "CSCs were characterized for the first time in acute myeloid leukemia (AML), in which cells with the CD34+/CD38− phenotype exhibited proliferative and self-renewal capacities similar to those of primary stem cells." (PMID 32028565, 2020). "In acute myeloid leukemia (AML), FASN expression is found to be significantly higher in the AML cohort when compared to granulocytes and CD34+ hematopoietic progenitor cells from healthy donors." (PMID 32872164, 2020). "In this single-center study, we prospectively assessed the CD34+CD38−CD123+ iLSC frequency at diagnosis in acute myeloid leukemia (AML) patients aged 60 years or older." (PMID 32384744, 2020). "Upregulation of SMARCA5 was previously observed in CD34+ hematopoietic progenitors of acute myeloid leukemia (AML) patients." (PMID 32197313, 2020). "CSCs have been identified as subpopulations of acute myeloid leukemia (AML) cells that express CD34, a specific surface marker." (PMID 32391363, 2020). "Leukemic stem cells (LSCs) were first described in acute myeloid leukemia (AML), where it was demonstrated that CD34+CD38− AML include a subpopulation of LSCs with a capacity to differentiate and self-renew." (PMID 31709180, 2019). "They separated patient-derived acute myeloid leukemia (AML) cells based on the expression of CD34 and CD38, which are the important markers for detection of immature cells in normal bone marrow." (PMID 35582573, 2019). "Elevated protein expressions of CD markers such as IL2RA/CD25, CXCR4/CD184, CD34 and CD56 are associated with adverse prognosis in acute myeloid leukemia (AML)." (PMID 31171000, 2019). "Genome-wide ChIPseq and ChIP-PCR experiments were performed to identify HIF1 and HIF2 binding sites in human acute myeloid leukemia (AML) cells and healthy CD34+ hematopoietic stem/progenitor cells." (PMID 31890203, 2019). "PTC596 has been reported to efficiently kill patient-derived CD34+CD38low/− stem/progenitor cells in acute myeloid leukemia (AML)." (PMID 29983879, 2018). "The biological relevance of SIRT6 in acute myeloid leukemia (AML) includes frequent up-regulation in tumor cells compared with normal CD34+hematopoietic progenitors." (PMID 29966233, 2018). "The CSCs of acute myeloid leukemia (AML) have a CD34+CD38- cell surface marker resembling that of normal hematopoietic stem cells (HSCs)." (PMID 28038467, 2017). "Lapidot and co-workers showed that the CD34+/CD38− subpopulation from acute myeloid leukemia (AML) was able to form leukemia after transplantation into NOD/SCID mice." (PMID 28209166, 2017).
acute myeloid leukemia (continued). "In myeloid neoplasms, such as acute myeloid leukemia (AML), the disease-initiating stem- and progenitor cells are considered to reside within a CD34+ compartment of the clone." (PMID 27582537, 2016). "We found a significant decrease of Cdh1 in primary acute myeloid leukemia (AML) blasts compared to normal CD34+ cells." (PMID 27374082, 2016). "EVs from acute myeloid leukemia- (AML-) blasts that are positive for the hematopoietic progenitor cell antigen CD34 have been reported to be biologically active." (PMID 26649044, 2016). "The in vitro effects of various FTIs (alpha-hydroxyfarnesylphosphonic acid, manumycin-A and SCH66336) were tested on CD34+ KG1a cell line and in primary acute myeloid leukemia (AML) cells from 64 patients." (PMID 27896224, 2016). "The identification of a small population of cells enriched with a tumor-initiating potential was first reported in Acute Myeloid Leukemia (AML) and it was based on the expression pattern of cell adhesion markers CD34 and CD38." (PMID 27457474, 2016). "An ongoing phase I clinical trial uses NK cells produced from CD34+ hematopoietic precursors to treat acute myeloid leukemia (AML) in elderly patients (CCMO nr." (PMID 25729364, 2015). "His results showed that a subtype of acute myeloid leukemia (AML) was able to reconstitute tumors in immune-compromised mice, but most importantly, these cells were isolated from a specific fraction (i.e. CD34+CD38−)." (PMID 27158195, 2015). "Single cell sorting and culture were performed in the various sets of hematopoietic stem cells including CD34+CD38- acute myeloid leukemia (AML) cell population (ASCs) from a total of 60 patients with AML, and 11 healthy controls." (PMID 25881148, 2015). "However, no substantial progress was made in the CSC hypothesis until Bonnet and Dick first isolated a subpopulation of human acute myeloid leukemia cells with a CD34++/CD38− phenotype, where CD34++ has a stronger affinity to the antigen." (PMID 24765137, 2014). "In acute myeloid leukemia (AML) CD34+ LSCs have been shown to be more akin to normal progenitors than CD34+ HSC with two populations identified as having engraftment potential in >80% of patients analysed." (PMID 23675967, 2013). "In the specific case of acute myeloid leukemia (AML), a small subpopulation of cancer stem cells have been identified in the CD34+CD38−CD123+ fraction." (PMID 22312362, 2012). "This technique was first used by Bonnet and Dick in 1997 when they demonstrated that only the CD34+CD38− subset of cells were capable of initiating human acute myeloid leukemia (AML) in immune-compromised mouse models." (PMID 20936110, 2011). "In acute myeloid leukemia (AML) in the BM, CD34-positive leukemic stem cells contribute to AML relapse by homing in on and expanding within the niche usually occupied by normal hematopoietic stem cells." (PMID 22069486, 2011). "CSCs reside in the CD34+/CD38− immunophenotypic subpopulation of acute myeloid leukemia (AML)." (PMID 41295979, 2026). "Flow cytometry on peripheral blood revealed a diagnosis of acute myeloid leukemia (AML) with the blast cells expressing CD11b, CD11c, CD15, CD13, CD24, CD33, CD34, CD117, CD123 and HLA-DR." (PMID 41300735, 2025). "In acute myeloid leukemia, the frequency of ALDH1+ cells was found to vary from 1 to 16%, and another study found that CD34+CD38− varied by 1000-fold in a cohort of 16 patients." (PMID 41228340, 2025). "Here we present the integrated metabolome, lipidome and transcriptome of human adult HSPCs (lineage−, CD34+, CD38−) upon differentiation, ageing and acute myeloid leukaemia." (PMID 40664811, 2025). "In contrast, while the CD34+CD38−/dim phenotype with aberrant marker expression (e.g., CD45RA, CD123, or CD26) is well-documented in CML and acute myeloid leukemia, a definitive LSC phenotype for lymphoid leukemia remains undefined." (PMID 40076750, 2025).